STAT3 (signal transducer and activator of transcription 3)
Diseases named in the same sentence as STAT3 in open-access papers (continued):
Sharing a sentence is not in itself a finding about the gene and the disease.
colon carcinoma (continued). "Cytokines such as CSF1 can activate RTK (CSF1R) and downstream STAT3 pathway, which can promote tumor migration and invasion in colon cancers." (PMID 35366939, 2022). "In agreement with above studies, our previous study indicated that STAT3 is an important target for colon cancer." (PMID 36207761, 2022). "Flow cytometry and TUNEL findings indicated that colon cancer cell apoptosis was inhibited after 50 μmol/L diosgenin was cotransfected with overexpressing STAT3 and overexpressing lentivirus." (PMID 35698571, 2022). "Western blot detection showed that after adding diosgenin to treat colon cancer cells, the expression of STAT3 was largely reduced." (PMID 35698571, 2022). "The STAT3 overexpression would counteract the inhibitory effect of 50 μmol/L diosgenin in both suppressing colon cancer cellular proliferation and migration and promoting apoptosis." (PMID 35698571, 2022). "Among the bioactive components studied in green tea, EGCG down-regulated STAT3 expression to induce apoptosis in colon cancer cells (SW480)." (PMID 36500365, 2022). "The possible mechanism is that MTCAFs activate the AKT and STAT3 signaling pathways in colon cancer cells via the ICAM-1/LFA-1axis." (PMID 36016615, 2022). "Signal transducer and activator of transcription 3 (STAT3) is a signaling molecule that promotes the development of colon cancer and is high expressed in colon cancer." (PMID 35698571, 2022). "A previous study reported that miR-181b is a direct regulator of PIAS3 that activates the STAT3 signaling pathway in colon cancer." (PMID 34980138, 2022). "In the case of colon cancer, the knockout of miR-139-5p activates STAT3, facilitating a pro-tumoral state." (PMID 35565420, 2022). "Inhibition of STAT3 phosphorylation was also found to induce programmed death of colon cancer cells and down-regulate the apoptotic protein Bcl-XL." (PMID 36686745, 2022). "In vivo experiments further verified that LINC00858 enhanced the tumorigenicity of colon cancer cells in vivo by regulating the RAD21/PCNP/STAT3/5 axis." (PMID 35468892, 2022). "Cotransfection experiments showed that STAT3 counteracted not only diosgenin's effect in inhibiting colon cancer cells' proliferation and migration but also that in promoting apoptosis." (PMID 35698571, 2022). "IL-22 not only activates STAT3 signaling pathway in epithelial cells and involved in tumorigenesis and CACs, it also appears to be involved in the resistance to chemotherapy in colon cancer cells." (PMID 35410210, 2022). "Jab1/CSN5 regulates unphosphorylated STAT3 DNA-binding activity via protein-protein interaction in colon cancer cells." (PMID 35315259, 2022). "It is predicted that diosgenin is likely to be involved in colon cancer proliferation and migration by targeting STAT3." (PMID 35698571, 2022). "STAT3 is known to be high-expressed in colon cancer and is a signaling molecule that promotes the development of colon cancer." (PMID 35698571, 2022). "Subsequently, in this study, 50 μmol/L diosgenin and STAT3 were cotransfected into colon cancer cells cultured in vitro to detect the regulatory effect of diosgenin on STAT3 and its influence on colon cancer cells." (PMID 35698571, 2022). "To explore the mechanism of the biological activity of pterostilbene on HT-29 colon cancer cells, we also examined its effect on the expression and activity of STAT3." (PMID 35056682, 2022). "The results showed that after 50 μmol/L diosgenin and STAT3 overexpressing lentivirus were cotransfected, the EdU positive rate of colon cancer cells was restored, which was notably upregulated compared with the control virus cotransfection group." (PMID 35698571, 2022). "After overexpression of STAT3, it would offset the apoptosis of colon cancer cells promoted by 50 μmol/L diosgenin." (PMID 35698571, 2022).
colon carcinoma (continued). "In summary, this study provides evidence that GOLPH3 is involved in regulating colon cancer cell invasion and migration through the STAT3 pathway and silencing GOLPH3 down-regulates ZEB1 and Integrin α3 expression to prevent CRC metastasis." (PMID 35372504, 2022). "After sIL-6R is released, on the one hand, it activates the JAK/STAT3 pathway or other signaling pathways in the tumor itself in an autocrine manner and promotes the proliferation and metastasis of colon cancer cells." (PMID 36270986, 2022). "EGCG/curcumin also inhibited JAK/STAT3 in tumor endothelial cells to inhibit angiogenesis and colon cancer metastasis." (PMID 36700235, 2022). "Another important finding of this study was that increased PCNP expression contributed to activation of the STAT3/5 pathway, which promoted the progression of colon cancer." (PMID 35468892, 2022). "Accordingly, macrophages have effect on colon tumor cells by IL-6 production and by activating STAT3 signaling pathway stimulate the production of IL-10." (PMID 35410210, 2022). "It indicated the promoting role of LINC00858 in colon cancer progression though activating PCNP-mediated STAT3/5 pathway by recruiting RAD21." (PMID 35468892, 2022). "Overexpression of STAT3 withdrew not only the diosgenin's effect in suppressing both colon cancer cells' proliferation and migration but also in apoptosis promotion." (PMID 35698571, 2022). "After knocking out STAT3 at the animal level, we will add diosgenin treatment to observe the development of colon cancer in animal models." (PMID 35698571, 2022). "Another study on 60 colon samples of different grades demonstrated that miR-1299 was negatively correlated to the TNM staging of colon cancer through targeting and inhibiting the expression of STAT3 and was closely related to colon cancer prognosis." (PMID 36497002, 2022). "For example, high expression of circSPARC in colon cancer contributed to accumulation of pro-phosphorylated (p)-STAT3 and facilitated its nuclear translocation via sponging miR-485-3p and recruitment of FUS." (PMID 35338119, 2022). "Many reports have shown the Stat3 activation in various tumor cell lines, including colon cancer cells; however, the direct implication of TGR5 in colonic carcinogenesis is still under debate." (PMID 35889921, 2022). "Tim-3 expression can be used as an independent prognostic factor in colon cancer patients, and Tim-3 can directly promote tumor growth through STAT3 or STAT3-pSTAT3 pathway." (PMID 36439090, 2022). "FN suppresses cell proliferation and invasion by inhibition of cyclin D1 and MMP2/9 expression via p-STAT3 inactivation in colon carcinoma cells." (PMID 34539403, 2021). "In order to ensure high quality and functionality, we used self-produced IL-26 which was functionally tested for STAT3 activation in a colonic carcinoma cell line." (PMID 34733265, 2021). "In conclusion, our results demonstrated that combination of AF and ICG-001 suppressed the proliferation and metastasis of colon cancer in vitro and in vivo by directly inhibiting STAT3 phosphorylation." (PMID 34900688, 2021). "We then used ChIP-seq analysis to evaluate the differential binding patterns of STAT3del and wild-type STAT3 in multiple colon cancer cells." (PMID 33535185, 2021). "Napa was shown to inhibit STAT3 transcription leading to a decrease in stem‐like properties of pancreatic and colon cancer cells." (PMID 33274592, 2021). "In conclusion, our results demonstrated that combination of AF and ICG-001 suppressed the proliferation and metastasis of colon cancer by inhibiting STAT3 phosphorylation." (PMID 34900688, 2021). "STEAP1 was up-regulated in the colon cancer cells with STAT3del compared to those with the wild type STAT3." (PMID 33535185, 2021). "Downregulation of USP7 mediated by signal transducer and activator of transcription 3 (STAT3) has been found in colon cancer." (PMID 34869041, 2021).
colon carcinoma (continued). "Our data reveal for the first time that Gal2 has a suppressive function on colon tumor growth likely via regulating the STAT3-mediated cell survival signaling." (PMID 33110234, 2021). "Mechanistically, we revealed that ZNF460 promotes metastasis through JAK2/STAT3 signaling pathway in colon cancer cells." (PMID 33976729, 2021). "STAT3 is a multifunctional transcription factor with an essential role in colon cancer progression and inflammation." (PMID 33557398, 2021). "In line with our results, gp130 inhibition with the SERM bazedoxifene has been reported to result in a reduction of interleukin-11 induced STAT3 phosphorylation, proliferation and viability, as well as organoid and xenograft growth in colon cancer." (PMID 32940862, 2021). "The increased activity of STAT3 is common in colon cancer, and STAT3 phosphorylation has been related to tumor cell survival and proliferation, and tumor angiogenesis." (PMID 34299314, 2021). "A signal transducer and activator of transcription factor 3 (STAT3) is found to be constitutively active in many cancers, including colon cancer, and plays a major role in cancer progression." (PMID 34946546, 2021). "We added PO- or PS-acet.-STAT3 or PS-STAT3-K685R peptides (approximately 1 μM) to the cultured colon cancer HCT116 cells." (PMID 33491667, 2021). "Here, we demonstrated that the absence of STAT1 promotes IL-17 activity during the early stages of colon cancer via STAT3 and that IL-17 neutralization prevented tumor growth." (PMID 34299314, 2021). "The results showed that downregulation of ZNF460 expression significantly decreased the p-JAK2 and p-STAT3 expression levels in colon cancer cells." (PMID 33976729, 2021). "The upregulation of CREPT and p-STAT3 in colon cancer tissue compared with the normal tissue was significantly correlated (R = 0.71, p = 0.038)." (PMID 33531691, 2021). "In accordance, immunohistochemical analysis of colon tumor sections indicated that activation of STAT3, highlighted by nuclear staining, is mainly located in proximity to adipose tissue of CRC patients with obesity." (PMID 34408135, 2021). "An analogue of curcumin, known as GO-Y030 can suppress STAT3 phosphorylation to impair CSC features in colon cancer and prevent its progression." (PMID 34769099, 2021). "(A) Representative immunohistochemistry images revealing activated STAT3 and P65 in colonic cancer tissue and precancerous tissue." (PMID 33882644, 2021). "We used the CRISPR-CAS9 gene editing system to delete the sequence encoding “NNGSLSAEFKHL” amino-acid sequence in the STAT3 gene in SW480, SW620 and HCT116 colon cancer cells and designated it as STAT3del." (PMID 33535185, 2021). "The upregulation of the phosphorylation of Tyr705 in STAT3 is frequently detected in human colon cancers and can induce upregulation of anti-apoptotic protein such as Bcl-2, Bcl-xL, and Mcl1 expressions to prevent apoptosis of tumor cells in multiple tumors." (PMID 34900688, 2021). "Mechanistically, we revealed that ZNF460 promotes the activation of the JAK2/STAT3 signaling pathway in colon cancer cells." (PMID 33976729, 2021). "Further studies reported that apatinib inhibited PD-L1 expression by targeting signal transducer and activator of transcription 3 (STAT3) in osteosarcoma, while promoted its expression to enhance anti-PD-1 therapy in colon cancer." (PMID 34429133, 2021). "Genetic and pharmacological studies confirmed that claudin-3 loss induces Wnt/β-catenin activation, which is further exacerbated by Stat-3-activation and helps promote colon cancer." (PMID 34638619, 2021). "(B) Representative western blotting revealing the expression of p‐P65, P65, p‐STAT3 and STAT3 in stages II and IV colonic tumor tissues." (PMID 33882644, 2021). "Consistently, immunofluorescence staining also showed higher p-STAT3 level in the colon tumors of Gal2-KO mice than those of WT mice." (PMID 33110234, 2021).
colon carcinoma (continued). "On the other hand, IL-6 can induce STAT3 phosphorylation in colon cancer cells with overexpressed RAB3C, which promotes the migration of colon cancer cells." (PMID 33718596, 2021). "For example, miR-181b can interact with STAT3 to regulate glycolysis in colon cancer cells and affect the growth in the mouse xenograft model of colon cancer." (PMID 33944652, 2021). "ChIP-qPCR analysis showed that the DNA-binding affinity of STAT3 was significantly reduced at the known target genes such as Snail, Spg20, Mmp3 in the colon cancer cells with STAT3del, especially in the SW480 cells with STAT3del." (PMID 33535185, 2021). "One study identified miR-1299 as an important role player in suppressing the growth of colon cancer cells via downregulation of the signal transducers and activators of transcription (STAT3)." (PMID 33937359, 2021). "The β-carotene suppresses IL-6/STAT3 axis and inhibits M2 polarization of macrophages to impair colon tumor progression." (PMID 34769099, 2021). "A study reported that the suppression of STAT3 activity significantly enhances the efficacy of doxorubicin in the induction of immunogenic cell death in CT26 colon cancer cells." (PMID 34946546, 2021). "Programmed death in colon cancer cells can be induced by inhibition of STAT3 phosphorylation, thereby downregulating the antiapoptotic proteins Bcl-XL and Mcl-1." (PMID 34539403, 2021). "Phase III data in colon cancer patients demonstrate that in patients with high levels of p‐STAT3 overall survival was greater in Napa‐treated patients." (PMID 33274592, 2021). "Similar to our results, STAT3 phosphorylation has been found to be suppressed by raloxifene in breast and colon cancer, thereby promoting apoptosis and decreasing cell viability." (PMID 32940862, 2021). "Inhibition of STAT3 phosphorylation, resulting in downregulation of antiapoptotic proteins Mcl-1 and Bcl-xL and induces programmed cell death in colon cancer cells." (PMID 34539403, 2021). "FKBP14 promotes the proliferation and migration of colon cancer cells by targeting the IL-6/STAT3 signaling pathway." (PMID 34722557, 2021). "Our conclusion is that ATP-induced P2 × 7 receptor activation promotes the migration and invasion of colon cancer cells, possibly via the activation of STAT3 pathway." (PMID 33330466, 2020). "The results indicate that the activation of P2 × 7 receptor promotes the invasion and migration of colon cancer cells by activating the STAT3 signaling." (PMID 33330466, 2020). "It was reported that activation of STAT3 suppressed cell apoptosis, and promoted cell migration and invasion, cell cycle arrest by modulating several genes’ expression in liver, ovarian and colon cancer." (PMID 32404045, 2020). "Using siRNA specifically targeting STAT3, we selectively silenced STAT3 expression in colon cancer cells, which was certified using western blot." (PMID 31953926, 2020). "Cytokine-mediated JAK/Stat3 pathway activation has been shown to promote excessive proliferation and invasion of colon cancer cells." (PMID 32317968, 2020). "RNA interference was performed to silence the expression of HOTAIR or STAT3 to explore their biological functions in colon cancer." (PMID 31953926, 2020). "STAT3 is reported constitutively activated in colon-cancer-initiating cells and play a significant role in colon cancer progression." (PMID 32957968, 2020). "To further understand the possible mechanism by which ultralow dose DPI reduces colon cancer, we evaluated the activation of tumor-promoting signaling pathways, such as STAT3, MAPK, and NF-κB, in IECs." (PMID 32550901, 2020). "Trichomicin inhibited TNFα-induced NF-kB phosphorylation and induced activation of Stat3-related signaling pathways in a dose-dependent manner in colon cancer cells." (PMID 32317968, 2020). "Withaferin A (WA), another natural compound, has been shown to inhibit colon cancer cell growth by blocking signal transducer and activator of transcription 3 (STAT3) transcriptional activity." (PMID 32630477, 2020).
colon carcinoma (continued). "Our data indicated that OCA treatment repressed the activation of JAK2/STAT3 pathway in colon cancer cells, which was further confirmed by IF staining, showing increased levels of STAT3 protein located in the cell cytoplasm." (PMID 33164339, 2020). "All of these results indicate that FXR activation inhibits JAK2/STAT3 pathway by regulating SOCS3 transcription in colon cancer cells." (PMID 33164339, 2020). "For example, Bufalin suppresses cell growth by inhibiting JAK-STAT3 signaling in colon-cancer cells, and convallatoxin promotes apoptosis and inhibits angiogenesis through inhibiting JAK2/STAT3 signaling in colon cancer cells." (PMID 33114727, 2020). "In prostate, gastric, and colon cancer cell models, piperine inhibited migration via STAT-3 downregulation, resulting in inhibition of metastasization." (PMID 33256185, 2020). "Matjaz R. suggested that the IL-6R/STAT3/miR-34a feedback loop promotes colon cancer metastasis by inducing EMT." (PMID 32358527, 2020). "An emerging body of evidence indicates that NF-κB and STAT3 have been identified as active participants in colon cancer progression and the inhibition of the activation of these two proteins has the potential to prevent and treat colon cancer." (PMID 32024285, 2020). "In the CAC model, FLCWK synergized with 5-FU to inhibit the phosphorylation of STAT3, preventing IL-6/STAT3 signal transduction and thus further inducing apoptosis and inhibition of colon cancer cell proliferation." (PMID 33082817, 2020). "Downregulation of MPC subunit expression via the signal transducer and activator of transcription 3 (STAT3) pathway attenuated IFNγ-mediated apoptosis of the colon cancer cells by preventing production of reactive oxygen species (ROS)." (PMID 32708919, 2020). "In contrast to this result, the phosphorylation state of STAT3 was either unchanged, as in the colon cancer cell lines, or increased, as in the case of MDA-MB-468 cell line." (PMID 33291686, 2020). "STAT3 expression and activity is dysregulated in many malignant cancers, including breast, skin, brain, and colon cancer." (PMID 32222879, 2020). "IL-6/STAT3 signalling plays an important role in the rate of occurrence and development of colon cancer." (PMID 33082817, 2020). "The WB results showed that IL-11 can induce the p-STAT3 expression in all three colon cancer cells, and this activation can be reversed by bazedoxifene." (PMID 30736824, 2019). "The proteins downstream of the STAT3 pathway, including cyclin D1, survivin and c-myc, also decreased correspondingly in all three colon cancer cell lines." (PMID 30736824, 2019). "In particular, HSP110 is a newly discovered player in the field of cancer aggressiveness that controls the STAT3 pathway in colon cancers and in B-cell lymphomas." (PMID 31861612, 2019). "Altogether, these data suggest that ROS induce CD80 expression via MAPK pathways that activate STAT3 in colon cancer epithelial cells." (PMID 31072360, 2019). "All these results confirmed that bazedoxifene exerted its inhibitory role in colon cancer cells through inhibition of the IL-11/GP130/STAT3 signaling pathway." (PMID 30736824, 2019). "The IL-11/GP130/STAT3 pathway is involved in drug resistance in a variety of human cancers, including colon cancer." (PMID 30736824, 2019). "Meanwhile, the levels of phosphorylated STAT3 in colon cancer cells was up-regulated with the treatment of CDEs derived from hypoxic tumor cells." (PMID 31402975, 2019). "An ever-increasing number of reports correlate excessive GP130/STAT3 signaling with the progression of colon cancer." (PMID 30736824, 2019). "Our data demonstrated that in colon cancer cells CD80 induction by oxidative stress was mediated by two different MAPK pathways converging to the transcription factor STAT3." (PMID 31072360, 2019).